CD4 (CD4 molecule)
Diseases named in the same sentence as CD4 in open-access papers (continued):
Sharing a sentence is not in itself a finding about the gene and the disease.
viral infection (continued). "Additionally, this conclusion provides an explanation of why CatG is present on the cell surface of B cells, CD4+, CD8+ T cells, dendritic cells, monocytes, neutrophils, and natural killer cells, indicating an innate immune (cellular) defense strategy against viral infection." (PMID 39339444, 2024). "The main factors involved in the benign nature of this infection are (i) low level of immune activation, (ii) relative preservation of specific CD4+ T-cell subsets from direct virus infection, and (iii) absence of microbial translocation from the gut to the systemic circulation." (PMID 39258922, 2024). "In the present study, the MPL + poly I:C-adjuvanted iPR8 vaccine induced higher levels of CD8/CD4 TCM and TEM residing in the lungs compared with the individual adjuvanted and nonadjuvanted vaccines, which conferred complete protection from severe disease outcomes upon viral infection." (PMID 37507413, 2023). "Thus, activated CD4+ T lymphocytes can differentiate into a Th response designed to fight bacterial or fungal antigens, while activated CD8+ T cells can differentiate into cytotoxic T cells to combat viral infections." (PMID 36678282, 2023). "It has been described, in agreement with our results, that antibodies against HCoVs did not correlate with cross-reactive CD4+ T-cells because they have not been recently generated, as observed with early CD4+ T-cell responses following yellow fever vaccination." (PMID 36992336, 2023). "Furthermore, LCMV-specific CD8+ T cells were depleted to a greater extent in mice with impaired IL-21 signaling, indicating that IL-21 produced by CD4+ T cells is necessary for sustained CD8+ T-cell effector activity and, consequently, for maintaining immunity to resolve persistent viral infection." (PMID 37649897, 2023). "For example, one might also consider that the plasma concentration of CD4, CD8, and CD3 lymphocytes that tend to decrease in this viral infection, but also in others, is potentially evident because of the increased migration of these cells at the gut epithelium–microbiota interface." (PMID 36835341, 2023). "Interestingly, no reports on CD4+ T cell immunity in patients with H5N6 virus infection currently exist." (PMID 37853397, 2023). "HIV-positive participants aged 18–59 years, with baseline CD4+ T-cell count of at least 200 cells per mL, and who were not pregnant, had no previous history of yellow fever vaccination or infection, and had no contraindication for yellow fever vaccination were recruited from the community." (PMID 37127045, 2023). "Even though the proportion of CD4+ CTL may increase in elderly individuals at least partly due to clonal expansion following repeated viral exposure, the majority of studies on CD4+ CTL, as well as their initial investigation in vivo, originated from the realm of viral infections." (PMID 37965314, 2023). "This suggests that the possible D7 protein-CD4 interaction-mediated impact on viral infections may be directly affected by CD4 protein rather than downstream immune molecule activation." (PMID 36070318, 2022). "Moreover, an in-depth assessment into how the transcriptional landscape of CD4+ T cells differs between acute and chronic viral infection at the single-cell level has not previously been explored." (PMID 36255051, 2022). "While CD101 has been investigated in chronic viral infection on CD8 T cell populations using the LCMV mouse model, its role on CD4 T cells has not been investigated in the rhesus macaque model and there have been no studies of CD101+ CD4 T cells in acute and chronic viral infection." (PMID 35867722, 2022). "Lastly, we investigated how a transcriptional map of CD4+ T cells that developed in response to viral infections could help interpreting the heterogeneity of CD4+ T cells differentiating in a non-infectious context." (PMID 35829695, 2022).
viral infection (continued). "In vivo and in vitro studies suggested that peripheral CD4highCD8low T cells might be derived from CD4+T cells and represent a subset of late differentiated effector CD4+ T cells, while CD4lowCD8high T cells might be derived from CD8+T cells activated during viral infection." (PMID 35712309, 2022). "Single-cell sequencing, tissue immunofluorescence staining, and adoptive transfer experiments indicate that viral infection-induced type I IFN signaling could inhibit CXCL9/10 production in myeloid cells, ultimately impairing pulmonary migration of Mtb-specific CD4+ T cells." (PMID 35672321, 2022). "Notably, viral infection augmented IFN-γ production in both NK and CD8+ T cells in Sash mice, but diminished its production in WT mice; meanwhile, IFN-γ production in CD4+ T cells was similar in WT and Sash mice." (PMID 35197951, 2022). "In addition, in other viral infections in pigs such as African swine fever virus (ASFV), it was demonstrated that UV-inactivated virus stimulated proliferation not only of CD4+ and CD8+ T cells but also of CD4+CD8+ double-positive T cells." (PMID 35281443, 2022). "In detail, TLR7 favors the production of cytokines involved in CD4+ T helper 17 (Th17) cell polarization (IL-1β, IL-6, and IL-23) after virus infection with MV and VSV, whereas TLR8 promotes the TH1-promoting cytokine response and type I IFN production after viral infection with ECMV." (PMID 36359340, 2022). "Recognition of SARS-CoV-2 peptides in the context of HLA class II molecules is essential for CD4+ T-cell activation and proliferation which, in turn, orchestrate the development of effector cellular (CD8+ T-cell) and humoral adaptive immune responses after viral infection and after vaccination." (PMID 34349756, 2021). "Resident and migratory DCs also display differences in the type of T cells they activate; for example, in viral infections, migratory DCs were shown to prime CD4+ but not CD8+ T cells in dLNs, whereas resident DCs prime CD8+ T cells in a delayed manner, helped by the already activated CD4+ T cells." (PMID 34065513, 2021). "However, measuring the CD4+/CD8+ cell ratios in the lungs and spleens of LDR-administered mice and sham-treated mice failed to establish any significant difference between the CD4+/CD8+ cell ratios in the 2 groups at the time of viral infection." (PMID 33974566, 2021). "Such an outcome could potentially be mediated by a mixture of memory CD4+ T cells, memory CD8+ T cells, and memory B cells specific for RBD producing anamnestic neutralizing antibodies, based on mechanisms of action in mouse models of other viral infections." (PMID 33408181, 2021). "While this assay is robust and moderately high throughput, it may not fully recapitulate Vpu expression or function during viral infection, where it acts in concert with other viral proteins to modulate CD4." (PMID 32376625, 2020). "Although our human study does not provide a causative link between granzyme-producing CD4+ or CD8+ T cells and irAE, we can speculate that these CTLs might be potentially harmful and their responses may be accelerated during virus infections." (PMID 32226027, 2020). "Notably, CD4+ T-cells in severe patients showed lower expression of the TNF superfamily ligands TNFSF10 (TRAIL) and TNFSF14 (LIGHT) and the surface protein SLAMF1 and KLRB1, all of which have roles in viral infections." (PMID 33178221, 2020). "Moreover, residence is a dominant feature of CD4+CD69+ memory T cells generated by viral infection in various non-lymphoid tissues." (PMID 32508808, 2020). "The importance of TGF-β in regulation of CD8+ T cell responses during chronic viral infection has been directly demonstrated in murine models; moreover, in SIV-infected macaques virus-specific CD8+ T cell frequencies correlate negatively with those of CD4+ Treg cells, a prominent source of TGF-β." (PMID 33329587, 2020).
viral infection (continued). "Interestingly, HEAL expression was absent in bystander and uninfected MDMs and CD4+ T cells, suggesting that viral infection upregulates HEAL." (PMID 32183241, 2020). "Interestingly, the models of viral infections in CD70−/− mice showed that the lack of CD70 expression mainly affects effector CD8+ but not CD4+ nor memory T cells, supporting our conclusions that FR70 monotherapy also mainly affected the CTLs." (PMID 33737923, 2020). "Indeed, this CD4+CD8+ T cell population exhibit properties of mature antigen-experienced memory/effector T cells, is characterized by the expression of IFNγ and plays a role in protection against viral infection." (PMID 31620134, 2019). "Because cells in the uninfected group experienced exactly the same trends, it could be concluded that the change of CD4/CD8 ratio resulted from the inherent property of these cells or from the culture system but not from the virus infection." (PMID 31014302, 2019). "Notably, there was no significant change in CD4 expression on cells isolated pre or post the control and exercise session at the time of viral infection (P = 0.84)." (PMID 31552706, 2019). "The total splenic and DLN cell number and the numbers of CD8+ T cells and macrophages in these organs were significantly increased during infection with vΔA55 compared to levels with control virus infection, while no significant changes were observed for CD4+ T cells, neutrophils, or NK cells." (PMID 30814284, 2019). "Further, the CD38 molecule resembles a homologous sequence of the Loop V3 region of gp120 that interacts with the CD4 molecule blocking the access of the virus to this receptor; and indeed, a soluble form of CD38 is being studied as a potential strategy against this viral infection." (PMID 31550271, 2019). "Therefore, regardless of acute viral infection, CD4+ and CD8+ T cells would be readily able to migrate and perform effector function." (PMID 29282904, 2018). "B (representative overlaid histogram and summary data of flow cytometry), resting naive CD4 T cells derived from HCV-infected patients had significantly higher expression of 8-oxoG DNA bases compared to HS, indicating an accumulation of DNA lesions during chronic viral infection." (PMID 29644094, 2018). "In addition, although the absence of IL-27 consistently reduces IL-10 producing CD4 T cells in multiple types of viral infections, the outcome for viral control is highly variable." (PMID 30044874, 2018). "However, these CD4 T cells with the altered activation state acquire the capability of producing IL-21, a key cytokine that enhances the GC response and also supports the CD8 T cell response; both are required for control of the viral infection." (PMID 29734372, 2018). "General, non-cognate driven activation of LN CD4 T cells could differ between cancer and a chronic viral infection like HIV, with a presumably differential impact in the generation of Tfh cell responses." (PMID 30319664, 2018). "Given the possibility that CD30 expression on CD4+ TEM and TTM subsets may be due to cellular activation, we sought to clarify if we were simply selecting a highly activated portion of CD4+ T cells, rather than a potential marker of viral infection." (PMID 29470552, 2018). "A more recent study shows that the vaccine rDEN2Δ30 induced stronger CD8+ T responses, but less CD4+ T cell responses than those to natural DENV2 infection, suggesting the differences between CD4+ and CD8+ T cell responses induced by vaccines compared to natural viruses infection." (PMID 30340377, 2018). "Interestingly, unlike our peptide stimulation assay, viral infection did not appear to stimulate CD8+ or CD4+ T cells to make TNF-α above background levels in any of the assay conditions." (PMID 28643775, 2017).
viral infection (continued). "CD4 CTL may also be involved more broadly in the regulation of immune responses, through regulatory T cell (Treg) function (to be discussed later) and may also be involved in other non-viral infections and anti-tumor responses." (PMID 28167943, 2017). "Thus, CD4+ CTL play a pivotal role restraining viral infection with tropism for MHC class II-positive target cells, as infected lung alveolar or airway epithelial cells, EBV-transformed B cells, or HIV-1-infected human CD4+ T cells." (PMID 28289418, 2017). "Similarly, CD4+ T cells are also known to perform a variety of functions in the development of immunity, such as facilitation of the formation and optimal recall of CD8+ T cells or even direct killing of infected cells during viral infection." (PMID 28066421, 2016). "High levels of antibodies in individuals with CD4<200 may result from chronic viral infection induced inflammation and high viral titers non-specifically stimulating PPS-binding, but non-functional, antibodies." (PMID 25908995, 2015). "Moreover, re-challenge of chimpanzees that had cleared a previous viral infection was poorly controlled in the absence of a functional CD4+ T-cell response." (PMID 24466045, 2014). "While exhaustion and dysfunction of anti-viral effector T cells have been suggested as a major factor in chronic viral infections, particularly the LCMV model in mice, the role of neutralizing antibodies, generated through CD4 help for B-cells in GCs may well be the ultimate determinant of outcome." (PMID 25610441, 2014). "Studies in HIV infected patients and SIV infected non-human primates have shown massive dissemination of viral infection in the gut mucosa during the primary acute stage of infection leading to severe and rapid CD4+ T cell depletion, which persists through all stages of infection." (PMID 25166758, 2014). "It is unclear whether the small number of p24+ cells found in CD4+ T-effector RA + cells (TEMRA, CCR7-CD45RO-) represents a reproducibly infectable population since CD4+ TEMRA cells are thought to be non-permissive for R5 virus infection." (PMID 24957778, 2014). "We show that continued CD28 expression is important for effector CD4+ T cells following infection; maintained CD28 is required for the expansion of T helper type 1 cells, and for the differentiation and maintenance of T follicular helper cells during viral infection." (PMID 25347065, 2014). "Consequently, CD4+ and CD8+ T cells play important roles in protection against viral infections." (PMID 24465897, 2014). "However, it has been shown that CD4+ T cell expression of Th2-type cytokines including IL-4 and IL-5 does not promote recovery from viral infection, but rather increases lung viral burdens." (PMID 25500584, 2014). "In order to determine whether Env mutants with PNGS mutations could be incorporated into viral particles and support viral infection, we generated pseudoviruses with the PNGS mutants of Env and tested the capacity of these pseudoviruses to infect TZM-bl cells (CD4+, CCR5+, and CXCR4+)." (PMID 23384254, 2013). "During influenza virus infection, DCs secrete antiviral cytokines to activate CD4+ and CD8+ T cells through a specific response with the production of neutralizing antibodies and secretion of antiviral cytokines, such as IFN-γ, which contribute to the elimination of viral infection." (PMID 23728719, 2013). "This extent of CCR5 down-regulation might be sufficient to affect virus infection, since studies with anti-CCR5 antibodies have demonstrated that their exposure to PBMC can drop the mean surface expression of CCR5 from CD4+ T-lymphocytes or U87-CCR5 cell cultures to 19–37% of control." (PMID 23935482, 2013).
viral infection (continued). "Much if not most of the attention on CD4+CTL has been focused on viral infections, and even a cursory review of the evolving concept of antiviral CD4+ killer T cells illustrates the difficulties to derive insights into the precise role and relevance of these cells in infectious disease in general." (PMID 23565245, 2013). "Despite recent studies showing the importance of regulating IL-4Rα expression on CD4+ T cells following parasitic infection in vivo, only few studies have addressed how the cytokine receptors for IL-4/IL-13 are regulated on CD8+ T cells following virus infection in vivo." (PMID 23383283, 2013). "However, recent studies have identified a distinctive population of CD4+ T cells that do express NKG2D, which could represent a particular cytotoxic effector population involved in viral infections and chronic diseases." (PMID 23947399, 2013). "Our finding that TL in CD4+ T cells specific for the non-recurring acute virus infection, VACV, was longer than TL in T cells specific for the acutely infecting but recurring exposure virus, IAV, supports our initial model in which recurring antigen exposures drive a more rapid TL decay with age." (PMID 23971624, 2013). "During the acute neuroinflammatory stage of TMEV infection, CD4+ Th1 T-cells appear to control the viral infection, although we did not notice significant differences in viral load in our experiment in day 7; therefore the observed protective role is unlikely to be related to this effect." (PMID 22348089, 2012). "Consistent with the hypothesis that HIV controllers are predisposed to a weak Treg response to chronic viral infections, we observed significantly higher CMV-specific CD4+ T cell responses in HIV controllers than non-controllers and HIV-uninfected individuals." (PMID 21305005, 2011). "Furthermore, SIV infection of the natural hosts in the wild show limited CD4 decline despite active viral replication, suggesting that virus infection per se does not lead to CD4 T cell destruction." (PMID 21255440, 2011). "Once activated, DC promote the stimulation of CD4 and CD8 T cells by inducing a specific response with the production of neutralizing antibodies and secretion of direct antiviral cytokines, such as IFN-α, which, together, contribute to elimination of viral infection." (PMID 21625541, 2011). "Another report has shown that PD-1 expressing CD4+ T cells during murine Mtb infection are not analogous to the functionally exhausted PD-1-expressing CD8+ T cells seen during chronic viral infections but rather are a highly proliferating, cytokine-producing population." (PMID 21509782, 2011). "Demyelination may be the result of (i) direct virus infection of oligodendrocytes independent of the host T‐cell response, (ii) CD4 or CD8 T cells directed to antigens not tolerized by these transgenes 37, 42, 43, or (iii) epitope spreading to myelin antigens." (PMID 17388949, 2007). "In this study, we systematically investigate whether and how Themis affects CD4+ T cells function during chronic LCMV infection, and report a novel role for Themis in differentially regulating TFH cell differentiation during early and late stages of chronic viral infection." (PMID 40777021, 2025). "Moreover, the increase in IL‐21‐producing CD4+ T cells in participants with diabetes, which are important in providing B cell help and in enhancing the survival and function of cytotoxic CD8+ T cells upon vaccination or viral infection, was accompanied by a concomitant increase in IL‐10 production." (PMID 41367201, 2025). "Besides this acute systemic viral infection, the acute local lung infection with influenza, the acute systemic bacterial L. pneumophila infection, and even the chronic systemic LCMV Cl13 infection all induced a CD4 T cell population equipped with enhanced responsiveness to cytokine stimulation." (PMID 40923840, 2025).